IL6 (interleukin 6)
Diseases named in the same sentence as IL6 in open-access papers (continued):
Sharing a sentence is not in itself a finding about the gene and the disease.
ischemic stroke (continued). "Reports have shown that expression of IL-6 in human patients after ischemic stroke is associated with the size of infarction." (PMID 22348126, 2012). "Furthermore, inflammatory markers, such as C-reactive protein (CRP) and interleukin 6 (IL-6), have been associated with the risk of ischemic strokes." (PMID 40231146, 2025). "IL-6 is also implicated in the remote vascular dysfunction associated with ischemic stroke." (PMID 40949500, 2025). "This association was further confirmed by findings from the LIMITS study, which observed an association between elevated levels of circulating IL-6 and the risk of recurrent ischaemic stroke, myocardial infarction or vascular death in 1244 radiologically confirmed lacunar stroke patients." (PMID 37685924, 2023). "Therefore, specific inhibition of the IL‐6/JAK‐1/pSTAT3 pathway in astrocytes is a potential therapeutic approach to alleviate the progression of ischemic stroke caused by folic acid deficiency." (PMID 36794521, 2023). "Increased levels of IL-6 have been frequently associated with poor outcome after ischemic stroke." (PMID 37260778, 2023). "In addition to biomarker and pathological studies (below), a genetic epidemiological (Mendelian randomization) study of genetic proxies for lower IL-6 activity demonstrated that reduced IL-6 activity was associated with a reduced risk of ischaemic stroke." (PMID 41541100, 2023). "Furthermore, a randomized controlled study of ischemic stroke patients demonstrated that tumor necrosis factor-α and the interleukins (IL), such as IL-1β, IL-6, and IL-20, were associated with inflammation in ischemic stroke." (PMID 37533068, 2023). "Furthermore, elevated levels of IL-6 in both CSF and blood have been associated with an increased risk of fever, which in turn causes tissue damage after ischemic stroke." (PMID 36699006, 2022). "However, it should be considered that TNF-α and IL-6 also play a role in protecting the brain parenchyma against damage caused by ischemic stroke in the subsequent ischemic stages." (PMID 36142524, 2022). "We recently demonstrated that IL6 trans-signaling is associated with the risk of ischemic stroke and the binary/ternary complex (B/T) ratio, improved risk classification measures in individuals otherwise classified as at low-intermediate risk for cardiovascular events." (PMID 34372806, 2021). "Accumulating evidence confirmed that IL-6 was associated with adverse outcomes of ischemic stroke." (PMID 33927687, 2021). "In a future perspective, dampening IL6-driven inflammation in the vessel wall with recombinant sgp130Fc could possibly be used to prevent ischemic stroke in patients at high risk of large vessel atherosclerosis." (PMID 33350884, 2021). "We previously demonstrated that the B/T ratio, a biomarker assessing the pro-inflammatory IL6 trans-signaling pathway, could predict an increased risk of incident ischemic stroke, pre-eminently in individuals with low LDL cholesterol." (PMID 34372806, 2021). "The results of marker discovery studies on plasma of ischemic patients presented markers, such as BNP, von Willebrand factor, ICAM-1, CRP, and interleukin-6, through biomarker research progress associated with causes of ischemic stroke, which differed from the biomarkers identified in our study." (PMID 32466277, 2020). "Pro-inflammatory cytokines including IL-1β and IL-6 are elevated in the ischemic stroke brain, which may cause morphological and functional changes in the constituent cell types of the brain." (PMID 30705764, 2019). "The increased inflammatory response caused by IL-6 might exacerbate the ischemic stroke induced brain injury, and the IL-6 overexpression was considered to be a biomarker of ischemic stroke outcome." (PMID 31652447, 2019). "Interestingly, an IL-6 gene variant has been identified as a predictor of ischemic stroke in an epidemiological study." (PMID 28656054, 2017).
ischemic stroke (continued). "And current available evidence argues against a pathogenic role of IL-6 in ischemic stroke." (PMID 24877133, 2014). "The risk of ischemic stroke can be influenced by genetic variation in the inflammatory agents, including Interleukin-33 (IL-33), interleukin 4 (IL-4), interleukin 6 (IL-6), intercellular adhesion molecule 1 (ICA M-1), E-selectin (E-sel), chemokine (C-C motif) ligand 11 (CCL11), lymphotoxin (LTA)." (PMID 24107076, 2013). "Ischemic stroke was independently associated with increased bacterial counts of Atopobium cluster and Lactobacillus ruminis, and decreased numbers of Lactobacillus sakei subgroup, changes in the prevalence of Lactobacillus ruminis were positively correlated with serum IL-6 levels." (PMID 36032153, 2022). "It was also shown that beside inhibiting inflammatory response by targeting IL-6 gene expression in patients with ischemic stroke, let-7f may suppress expression of gene encoding MTHFR leading to low cellular MTHFR levels and excessive production of reactive oxygen species." (PMID 35562921, 2022). "Additionally, in a study about the relationship between ex vivo cytokine synthesis and 3-month outcomes after ischemic stroke, decreased release of IP-10, TNFα, IL-1β, and IL-12; increased release of IL-10 and IL-8; and higher plasma IL-6 levels were associated with poor outcomes." (PMID 36439158, 2022). "IL-20 may be associated with the increased IL-6 levels in serum after ischemic stroke." (PMID 35173738, 2022). "IL-6 plays an important and many-faceted role in atherothrombosis including MI and ischemic stroke, and the IL-6 system represent a promising but still evolving therapeutic approach." (PMID 41543641, 2026). "Therapeutic strategies targeting the IL-6 system in atherothrombosis including MI and ischemic stroke represent a promising but still evolving therapeutic approach." (PMID 41543641, 2026). "Even cytokines considered beneficial, such as IL-6 and IL-10, which promote angiogenesis and functional recovery, are potential therapeutic targets for ischemic stroke." (PMID 40364646, 2026). "In ischemic stroke, both neurons, astrocytes and microglia cells can produce IL-6, indicating its broader involvement in neuroinflammation." (PMID 41543641, 2026). "The elevated levels of IL-6 observed on day 30 post-treatment raise important considerations regarding the immune response and the long-term effects of stem cell therapy after ischemic stroke." (PMID 41583506, 2026). "IL-6 is a multifunctional cytokine with a central role in the acute-phase response to ischemic stroke." (PMID 40869247, 2025). "In ischemic stroke-induced neuroinflammation, IL-1β, IL-6 and TNF-α are three pro-inflammatory cytokines." (PMID 40004043, 2025). "ELISA results revealed significant increases in the pro-inflammatory cytokines TNF-α, IL-1β, and IL-6 in brain tissue after ischemic stroke." (PMID 40400029, 2025). "For example, following ischemic stroke induction in male Wistar rats, α-pinene administration significantly reduced IL-6 concentration in the hippocampus, cortex, and striatum." (PMID 40147520, 2025). "Mechanistically, ischemic stroke induces the upregulation of pro-inflammatory cytokines, particularly interleukin-6 (IL-6), which stimulates fibrinogen overexpression." (PMID 40376152, 2025). "Elevated levels of IL-6 and TNF-alpha during the acute phase of ischemic stroke have been strongly associated with more severe initial disability." (PMID 39859987, 2025). "Microglia are polarized to M1 subtype within a short period of time after ischemic stroke, thereby secreting various pro-inflammatory factors, including IL-1β, IL-6, IL-18 and TNF-α." (PMID 38421829, 2024). "IL6 has been described to have a bidirectional role in ischemic stroke, being both harmful and protective, while IL11 seem to have a protective role after ischemic stroke, despite having controversial roles in other processes such as fibrosis and inflammation." (PMID 37378751, 2024).
ischemic stroke (continued). "Our findings are consistent with previous studies, describing pericyte production of IL6 as early as 2 h after hypoxic treatment and Il11 expression 24 h after ischemic stroke." (PMID 37378751, 2024). "Microglial activation exacerbates cerebral tissue damage in ischemic stroke by leading to the release of pro-inflammatory cytokines such as interleukin-1 beta (IL-1β), IL-6, and tumor necrosis factor-alpha (TNF-α)." (PMID 39057078, 2024). "In an ischemic stroke, pro-inflammatory cytokines, containing IL-1β, IL-6, and TNF-α, are released from glial cells and/or neurons and trigger the inflammation." (PMID 38421829, 2024). "Within minutes after ischemic stroke, microglia are activated in an M1-like phenotype and release pro-inflammatory mediators, such as IL-6, TNF-α, iNOS, ROS, leading to the break of the BBB." (PMID 38879549, 2024). "Interleukins such as TNF-α, IL-2, IL-4, IL-6 and IL-10, secreted by lymphocytes, play an important role in the pathogenesis and prognosis of ischemic stroke." (PMID 39204113, 2024). "The potential of the application of IL-6 as a therapeutic agent for ischemic stroke has been a subject of interest." (PMID 38104193, 2023). "Immediately after ischemic stroke, immune cells in the central nervous system are excessively activated, leading to the release of several inflammatory factors, such as IL‐1β, IL‐6, and TNF‐α." (PMID 37062886, 2023). "Interleukin-6 (IL-6) levels rise following ischemic stroke from affected neurons, astrocytes, and microglia." (PMID 38178909, 2023). "Studies have shown that EP can reduce proinflammatory cytokines, such as TNF‐α and IL‐6, thereby inhibiting inflammation in ischemic stroke." (PMID 37143406, 2023). "For example, in the Northern Manhattan Study, higher IL-6 levels were associated with poorer cognitive function, as assessed by the MMSE, and interleukin-12 (IL-12) levels were found to be elevated in ischemic stroke patients with cognitive decline." (PMID 36673655, 2023). "All this reveals the clinical value of HBOT as a treatment for ischemic stroke which can modulate inflammatory responses, reduce IL-6 and TNF-α expression, and protect against ADRs." (PMID 37250560, 2023). "Following an ischemic stroke, M1-like microglia release proinflammatory cytokines such as IL-1β, IL-6, and TNF-α, as well as nitric oxide synthase, activating nuclear NF-κB and causing subsequent brain injury." (PMID 36793730, 2023). "Ischemic stroke pathogenesis is heavily influenced by IL-6 and has been demonstrated as the early marker of acute ischemic stroke." (PMID 37229192, 2023). "Recently, the utility of the binary/ternary (B/T) ratio in measuring IL‐6 inflammatory signaling to predict ischemic stroke has been elucidated." (PMID 36478506, 2023). "As reported recently in a clinical study, NBP combination with Edaravone treatment significantly decreased serum Tumor necrosis factor-α (TNF- α), C-reactive protein (CRP), and Interleukin-6 (IL-6) levels of ischemic stroke patients." (PMID 37243759, 2023). "IL-6 is an important proinflammatory cytokine that can promote the inflammatory response of damaged cells in ischaemic stroke." (PMID 36873429, 2023). "Nevertheless, when compared to the ischemic stroke, only several studies analyzed IL‐6 and IL‐10 in the ICH setting, and only a few showed correlations with neuroimaging variables." (PMID 35762501, 2023). "On the other hand, in ischemic stroke models, AhR exacerbates infarct formation, and downregulated IL-1β and IL-6 expression was detected in AhR KO mice." (PMID 36797786, 2023). "Numerous studies have shown that the level of IL-6 increases in cerebrospinal fluid (CSF) and peripheral blood after ischemic stroke." (PMID 36127663, 2022). "This table outlines cell-based preclinical trials finding regulatory effects on IL-6 expression as a mechanism to enhance ischemic stroke recovery." (PMID 36555094, 2022).
ischemic stroke (continued). "The study showed a positive relationship between IL-6 levels and these variables, demonstrating the promising use of IL-6 as a biomarker to assess long-term prognosis after ischemic stroke." (PMID 36699006, 2022). "Per our findings, IL-6 has been identified as a prognostic marker for ischemic stroke, as it was correlated with worsened ischemic brain injury and outcome in clinical and preclinical studies." (PMID 36085043, 2022). "During ischemic stroke, the expression of interleukin-6 (IL-6) in cells increases hepcidin through the JAK/STAT3 pathway, which causes FPN1 degradation, resulting in reduced iron release and thus intensified iron accumulation in cells." (PMID 36425577, 2022). "A cohort study found that elevated IL-6 levels were closely related to ICAS progression in patients with ischemic stroke." (PMID 36212641, 2022). "The dysregulation of IL-6 is closely related to the occurrence and outcome of many clinical diseases, including coronary heart disease, leukemia, hypertension, ischemic stroke and so on." (PMID 35173738, 2022). "Numerous studies have reported that different inflammatory and cardiogenic biomarkers (e.g., IL-6 and MMP-9) are closely associated with ischemic stroke and its functional prognosis." (PMID 36127663, 2022). "In conclusion, IL-6 has a dual effect in ischemic stroke, acting as an inflammatory factor in the acute stage and a neurotrophic mediator in the subacute and prolonged phase." (PMID 35173738, 2022). "Studies have shown that the expression of IL-6 and hs-CRP is upregulated after ischemic stroke, which are associated with intestinal flora disorders." (PMID 36389137, 2022). "Consistent with the network pharmacology findings, in the current study, it is revealed that IL-1β, TNF-α, IL-6, and IL-4 were significantly increased in the cerebral cortex and hippocampus after ischemic stroke." (PMID 36338345, 2022). "The role of IL-6 in ischemic stroke has been clarified less than other well-defined cytokines in the previous studies." (PMID 35911644, 2022). "When treated with human embryonic stem cell-derived and umbilical cord MSCs, animal models of ischemic stroke show decreased IL-6 mRNA relates to increased neurogenesis, angiogenesis, and decreased apoptosis." (PMID 36555094, 2022). "Other studies have also shown that patients who develop secondary infections after ischemic stroke show higher IL‐1β and IL‐6 blood concentrations on hospital admission and along the first 3 days after hospitalization, respectively." (PMID 35971650, 2022). "Nevertheless, polyphenols exhibited anti-inflammatory properties in obese mice after ischemic stroke, by reducing the elevation of pro-inflammatory markers in the brain including IL-1β, IL-6, MCP-1 and TNF-α." (PMID 35624723, 2022). "In experimental models of ischemic stroke, HPA system activity is associated with neuroinflammation, mediated by increased expression of pro-inflammatory cytokines TNFα, IL1β, and IL6." (PMID 34948340, 2021). "Many of these studies implicate IL-6 as a key contributing factor in the pathogenesis of ischemic stroke, however, some of the research studies faintly underscore the contrary." (PMID 34691061, 2021). "Clinical studies showed that ischemic stroke led to increased levels of IL-1β, IL-6, and TGF-β in cerebrospinal fluid, blood, and brain tissue of patients." (PMID 34408211, 2021). "A previous study has shown that cytokines, like IL‐6, can contribute to thromboembolic events and plaque disruption, which is the key promoter of ischemic stroke." (PMID 33998177, 2021). "Increased IL6 levels in the circulation and in the central nervous system have been demonstrated in the acute phase of ischemic stroke." (PMID 34372806, 2021). "Ischemic stroke acutely increases the levels of circulating IL-6 in experimental models, highlighting the potential of this molecule as a therapeutic target." (PMID 33770265, 2021).
ischemic stroke (continued). "Serum IL-6 routinely predicts the severity of the CNS lesions as well as the clinical outcome in ischemic stroke patients." (PMID 33668216, 2021). "Immediately after ischemic stroke, A1 astrocytes produce and secrete several proinflammatory mediators, such as IL-6, TNF-α, IL-1α, IL-1β, and IFN-γ." (PMID 34211624, 2021). "We showed that salivary TNF-α and IL-6 were significantly higher, whereas IL-10 content was statistically lower in ischemic stroke patients than healthy controls." (PMID 34433866, 2021). "Previous work from our group has demonstrated that Poldip2 depletion attenuates TNF and IL-6 levels following ischemic stroke, possibly via regulation of NFκB33." (PMID 33692398, 2021). "Using the very sensitive single-molecule array (simoa) technique, we determined plasma NF-L concentrations in ischemic stroke and TIA patients, and healthy controls and their association with disability scores, functional outcome, S100B, and IL-6 levels." (PMID 32595585, 2020). "Interleukin‐6 (IL‐6) is among the inflammatory mediators exhibiting elevated levels in ischemic stroke (IS) patients." (PMID 32583980, 2020). "Our results showed a similar expression pattern, specifically a reduction of IL-6 levels in the group of ischemic stroke with previous TIA up to 24 h." (PMID 33192985, 2020). "Interleukin-6 (IL-6) is a pleiotropic cytokine that plays a crucial role in the pathogenesis of various autoimmune and neurological disorders, including the ischemic stroke." (PMID 33238363, 2020). "Changes of the IL-4 serum concentration, together with increase of the IL-6 serum levels, have been reported as diagnostically valuable in the acute phase of ischemic stroke." (PMID 31701356, 2020). "The infection markers and inflammatory molecules, such as CRP, WBC, and IL‐6 were suggested to be biomarkers for outcome of ischemic stroke." (PMID 32196744, 2020). "It has been demonstrated that IL-6 is neuroprotective in cerebral ischemia, so it is plausible that exercise-induced IL-6 release contributes to the protection against ischemic stroke." (PMID 33317180, 2020). "The activated microglia subsequently release chemokines, cytotoxic mediators, and cytokines, including IL-1β, TNF-α and IL-6, triggering the inflammatory cascade after an ischemic stroke, thus further exacerbating neuroinflammatory damage." (PMID 32419986, 2020). "Chemokines attract neutrophils into ischemic tissues and stimulate the expression of IL-6 and intercellular adhesion molecules following ischemic stroke." (PMID 32153408, 2020). "Various blood-based biomarkers were found to be significantly associated with ischemic stroke from cardioembolic etiology including BNP/NT-proBNP, d-dimer, CRP, TNF-α, IL-6, and IL-1β." (PMID 33050269, 2020). "NSCs subjected to IL-6 pre-treatment demonstrated a reduction in grafted-cell death by 62% when transplanted into ischemic stroke mouse models." (PMID 33238363, 2020). "IL-6 is a proinflammatory cytokine secreted by microglia or astrocytes, depending on the acute or subacute phase of ischemic stroke, respectively." (PMID 31701356, 2020). "In hemorrhagic stroke, IL-6 level was increased between days 1 and 4, although the level was lower compared to the ischemic stroke." (PMID 31701356, 2020). "AMD3100 administration also results in the significant reduction of IFN-γ, TNF-α and IL-6 in the acute stage of ischemic stroke or after spinal cord injury." (PMID 33013914, 2020). "IL-1β and IL-6 increased at 1 day and 3 days after ischemic stroke in both groups, with a peak at 1 day after ischemic stroke." (PMID 30705764, 2019). "The anti-inflammatory role and thus the protective effect of IL-6 in ischemic stroke is supported by a previous study, in which repetitive i.v. administration of IL-6 protein ameliorated the behavioral outcome after pMCAo in mice." (PMID 31372938, 2019).